ECM1 (extracellular matrix protein 1)
Diseases named in the same sentence as ECM1 in open-access papers (continued):
Sharing a sentence is not in itself a finding about the gene and the disease.
tumor (78 papers, 2005 to 2026). "Integrin subunit member 3 (ITGA3), which acts as an adhesion molecule and is also involved in tumor biology, as well as the extracellular matrix protein 1 (ECM1), is associated with endochondral bone formation and angiogenesis." (PMID 40013338, 2025). "As the component of the extracellular matrix (ECM), the detailed mechanism associated with the ECM1-mediated tumor microenvironment remodeling is also unclear." (PMID 36145166, 2022). "ECM1 upregulation was associated with a significant increase in both tumor volume and weight (–C), while Western blotting revealed increased Vimentin expression and reduced E-cadherin expression in ECM1-overexpressing tumors." (PMID 35574325, 2022). "To determine which subtype of ECM1 contributes to tumor growth, we delivered cDNAs encoding hemagglutinin (HA)-tagged ECM1a or ECM1b into A8i cells and established the A8i-A and A8i-B cell lines, respectively." (PMID 34244494, 2021). "The enhancer-like lncRNA FALEC, located in close proximity to the tumor metastasis-associated ECM1 gene, has attracted our attention." (PMID 30984243, 2019). "ECM1 encodes a soluble protein that is involved in endochondral bone formation, angiogenesis, and tumor biology." (PMID 28086821, 2017). "ECM-1 is a glycoprotein and plays a role in angiogenesis, and has been implicated in tumor progression." (PMID 27487181, 2016). "Moreover, DKK3, TGFB1 and ECM1 have acted as immune-associated genes in the PCa tumour microenvironment." (PMID 38855324, 2024). "It has been found that the expression of ECM1 may be associated with BCa progression, which was confirmed by the potential anti-tumor effects observed in siRNA gene silencing experiments." (PMID 36765767, 2023). "The secretory glycoprotein, extracellular matrix protein 1 (ECM1), is associated with physiological processes including angiogenesis, the proliferation of epithelial cells, and skin differentiation, in addition to playing a role in tumor progression." (PMID 35574325, 2022). "The correlation of Dkk-3 and ECM-1 in cancer stroma might reflect a situation where the loss of Dkk-3 in tumor cells leads to increased expression of stromal Dkk-3 and ECM-1 in a homeostatic response that prevents tumor progression." (PMID 29858602, 2018). "In addition, ECM1 protein expression was also closely associated with depth of tumor invasion and TNM stage (P <0.05, respectively)." (PMID 24779890, 2014). "Whether ECM1 regulates metastasis associated genes, or interacts with other extracellular matrix proteins, or both, or is involved in tumor cells migration is currently unknown." (PMID 22284579, 2012). "By inhibiting IKK/IκB phosphorylation, WA prevents NF-κB activation, reducing ECM1 expression, a key factor in cisplatin resistance and tumor progression." (PMID 39949780, 2025). "Overall, our study reveals the molecular mechanism by which osteoblast‐secreted ECM1 in the bone microenvironment under anti‐androgen therapy pressure drives tumor resistance through the ECM1/ENO1/MAPK signaling axis in BMPC." (PMID 39563492, 2025). "Many studies have reported that ECM1 protein has various biological functions and is involved in processes such as embryonic cartilage formation, skin lesions, angiogenesis, and tumor progression." (PMID 38725854, 2024). "D-sEVs treatment also significantly enhances ECM1-mediated BC metastasis and growth in mouse models, as evidenced by the elevated tumor levels of MMP3 and S100A/B." (PMID 38402239, 2024). "ECM1 is a glycoprotein that can induce tumor growth by promoting angiogenesis or enhancing epidermal growth factor signaling." (PMID 37764869, 2023). "The relative expression of KISS1, FREM2, and ECM1 were in the pyramidal pattern, implying that maximal expression was in the tumor area." (PMID 38062443, 2023). "Extracellular matrix protein 1 (ECM1), as a secretory glycoprotein, regulates numerous cellular mechanisms such as angiogenesis, epithelial cell growth, and tumor progression." (PMID 37580737, 2023).
tumor (continued). "There was ECM1 up regulation in CRC cancer tissues that was correlated with tumor size, lymph node metastasis, and TNM staging." (PMID 37580737, 2023). "Another TNBC secretome protein, ECM1, was found to induce angiogenesis and to promote tumor cell proliferation through EGFR signaling, which conferred resistance to trastuzumab." (PMID 36768435, 2023). "The rate of ECM1 copy number amplification was about 19%, 19%, 15%, and 8% in the Clinical Proteomic Tumor Analysis Consortium (CPTAC), METABRIC, TCGA, and National Institute of Health and Medical Research (INSERM), respectively." (PMID 35784388, 2022). "A high level of ECM1 in stroma can induce the malignant transformation of NFs and transfer tumor signals to promote tumor progression." (PMID 36145166, 2022). "Treatment with both CDDP and WA further slowed the tumor growth, particularly at the late stage of tumor growth, and tumor volume was eventually reduced compared with the data from the first injection in ECM1 silencing A2780cis cells." (PMID 36145166, 2022). "Previously, ECM1 was found to influence various epithelial malignancies’ progression through the modulation of cellular proliferative activity, tumor metastasis and drug resistance." (PMID 36408224, 2022). "In our previous study, we found that high expression of ECM1 was correlated with tumor size, lymph node status and TNM stage in CRC patients and functionally promoted CRC cells proliferation, invasion and migration." (PMID 36408224, 2022). "Our study shows that ECM1 activates NFs to transform cells with characteristics of CAFs, which induces tumor microenvironment reconstruction and transmits drug resistance signals between cancer cells and tumor microenvironmental cells." (PMID 36145166, 2022). "An initial analysis of the Oncomine database revealed ECM1 to be highly upregulated in CRC patient tumor tissues as compared to normal tissue samples." (PMID 35574325, 2022). "Upregulation of ECM1 was correlated with tumor size, lymph node status and TNM stage in CRC patients." (PMID 35574325, 2022). "More recent studies, however, have emphasized the functional importance of ECM1 as a regulator of tumor development, progression, and recurrence." (PMID 35574325, 2022). "To validate the previous results in vitro, we analyzed the expression of ECM1 and p65 in xenograft tumor tissues derived from animal experiments, and found that WA treatment largely suppressed the expression of ECM1 induced by cisplatin." (PMID 36145166, 2022). "Monitoring these mice revealed that the knockdown of ECM1 significantly reduced tumor weight and volume." (PMID 36408224, 2022). "High levels of ECM1 in stroma can induce the malignant transformation of NFs and transfer tumor signals to promote tumor progression." (PMID 36145166, 2022). "ECM1 is overexpressed in multiple tumours, enabling ECM1-based epitopes to be broadly applied in diverse types of cancer." (PMID 33910591, 2021). "It has been shown that the GC tumor tissues had significantly higher levels of ECM1 expressions compared with normal margins." (PMID 32467737, 2020). "Ultimately, we performed gene set enrichment analysis (GSEA), protein-protein interaction (PPI) networks, and Bayesian networks (BNs) to explore the underlying mechanisms by which ECM1, CRYAB, CGNL1, and GPX3 are involved in tumor progression." (PMID 32292720, 2020). "There were also significant correlations between ECM1 expression, tumor depth of invasion, and stage." (PMID 32467737, 2020). "It has been observed that there were correlations between high ECM1 levels, tumor relapse, poor survival, and advanced stages of tumor among GC patients." (PMID 32467737, 2020). "ECM1 has been regarded as a component or physical barrier in the extracellular matrix, and a recent study found ECM1 to be important in regulating the tumor microenvironment." (PMID 32157214, 2020).
tumor (continued). "ECM-1 is overexpressed in many types of cancer and in most cases it has a tumor-promoting effect, correlating with increased metastasis and poor prognosis." (PMID 29858602, 2018). "Although many studies have reported that ECM1 affected not only the malignant cellular proliferation, but the cancer cell migration and invasion, the exact mechanisms by which ECM1 promoted tumor progression remained unclear." (PMID 27460906, 2016). "To observe the effect of ECM1 on cell proliferation in vivo, we tested the relationship of ECM1 expression to xenograft tumor formation in BALB/c nude mice." (PMID 25499743, 2014). "ECM1 protein was specifically expressed in the cytoplasm of tumor cells, with scattered expression in cell membrane; whereas, the nucleus had no staining." (PMID 24779890, 2014). "Six genes were selected as tumor suppressor gene candidates, among which, ECM1, ATF5 and EOMES are confirmed via siRNA experiments to have potential anti-cancer functions." (PMID 25517360, 2014). "As a tumor-derived protein, ECM1 was previously reported to be over-expressed in various malignant epithelial tumors, and tumors with lymph node metastases were more likely to be ECM1-positive; although the exact role of this protein was still controversial." (PMID 24779890, 2014). "In BT-474 cells overexpressing ECM1, tumor formation efficiency was significantly increased, whereas tumorigenic potential of the BT-474 TR cells was significantly decreased after ECM1 silencing." (PMID 25499743, 2014). "The protein expression of ECM1 in tumor specimen was correlated with depth of tumor invasion and TNM stage (Fisher’s exact test, P <0.001 and P = 0.002, respectively)." (PMID 24779890, 2014). "Furthermore, micro‐CT scanning and Hematoxylin‐eosin (H&E) staining of mouse tibiae harvested in the 8th week suggested that the ECM1 pAb delayed tumor progression and reduced tumor lesions volume." (PMID 39563492, 2025). "Furthermore, inhibiting ECM1 or utilizing the ENO1‐targeting inhibitor phosphonoacetohydroxamate (PhAH) significantly restores tumor cell sensitivity to ENZ." (PMID 39563492, 2025). "However, under the influence of the drug, osteoblasts secrete increased levels of ECM1 protein, which binds to the surface of tumor cells and activates the MAPK signaling pathway, promoting cell proliferation and causing treatment resistance." (PMID 39563492, 2025). "The inhibitory effect of ECM1 on docetaxel‐induced tumor cell apoptosis was also restored by PhAH." (PMID 39563492, 2025). "The findings indicated ECM1 gene as an immune-related marker through its involvement in macrophage polarisation and the observed significant differences in macrophage infiltration between tumour and non-tumour samples." (PMID 40349011, 2025). "Furthermore, different highly O-glycosylated protein-coding genes, such as mmp9, ecm1 and ankyrin-2, were upregulated in 4T1/Tn+ tumor cells." (PMID 38245559, 2024). "Furthermore, this study reports that different highly O-glycosylated protein-coding genes, such as mmp9, ecm1, and ankyrin-2 were upregulated in 4T1/Tn+ tumor cells." (PMID 38245559, 2024). "Furthermore, different highly O-glycosylated protein coding genes, such as mmp9, ecm1 and ank2, were upregulated in 4T1/Tn+ tumor cells." (PMID 38245559, 2024). "The observed increase in ECM1 levels within the tumor can be attributed to multiple factors, including the enhanced delivery of ECM1 by sEVs to the tumor, increased release of ECM1 from tumor cells, and elevated levels of ECM1 present in sEVs within the tumor microenvironment." (PMID 38402239, 2024). "With this DIU tool, we successfully detected a DIU gene ECM1 between tumor and normal samples and showed that the two isoforms of ECM1 might play different roles in tumor." (PMID 37741817, 2023). "We identify and experimentally validate a differential isoform usage gene ECM1, and further show that its isoform ECM1b may be a tumor-suppressor in laryngocarcinoma." (PMID 37741817, 2023).
tumor (continued). "In addition, much attention has been paid to the role of ECM1 in tumor biology, particularly its microenvironment as an alternative to tumor-directed therapy." (PMID 36553077, 2022). "Moreover, we found ECM1 to be closely correlated with CRC patient tumor size, TNM staging and lymph node metastasis." (PMID 35574325, 2022). "Moreover, secretory ECM1 from cancer cells can activate NFs to display characteristics of CAFs, which promotes tumor progression and cisplatin resistance." (PMID 36145166, 2022). "In addition, WA reverses cisplatin resistance by targeting both tumor cells and the tumor microenvironment through IKK/IκB/NF-κB signaling to reduce the expression of the ECM1 protein." (PMID 36145166, 2022). "Because ECM1 is a secreted protein, to assess the effect of ECM1 on the tumor microenvironment, we first detected the secreted ECM1 in CMs of different cancer cells, and found that ECM1 was highly secreted in A8, Hey, and A2780-ECM1 cells compared with in ECM1 knockdown and A2780 cells." (PMID 36145166, 2022). "Enforced ECM1 expression promoted colony formation and chemotactic migration of tumour lines." (PMID 35821197, 2022). "Tumor cell growth, migration, and apoptosis via regulation of receptor interaction were reported to be related to the extracellular matrix protein 1 (ECM1) expression, which was considered as a predictive parameter in the carcinogenesis and postoperative recurrence of BLCA." (PMID 35799606, 2022). "Finally, we established a subcutaneous CRC tumor xenograft model system which demonstrated the ability of ECM1 overexpression to promote enhanced in vivo tumor growth, suggesting that ECM1 functions in an oncogenic manner in CRC." (PMID 35574325, 2022). "Notably, several genes related to matrix composition and immune cell recruitment were upregulated in squamous cells (Anxa1, Ecm1, Il1rn, Itgb4), as well as genes that are reported to be tumor suppressors (Serpin5b, Phlda3)." (PMID 35600339, 2022). "Taken together, FAL1 and ECM1 upregulated expression was frequently observed in the young patient group, and this upregulation might contribute to defining tumour behaviour in the young patient group." (PMID 34203279, 2021). "As another example, in TSCC, the tumor suppressive lncRNA FALEC could recruit EZH2 at the promoter regions of the oncogene ECM1 (extracellular matrix protein 1), epigenetically repressing ECM1 expression, and thereby repressing malignant behaviors." (PMID 34063159, 2021). "The results demonstrated that LA/DC-CTL could induce immune responses against tumours in an HLA-A2-restricted and ECM1-specific manner." (PMID 33910591, 2021). "On the contrary, down-regulating the expression of ECM1 could significantly suppress the proliferation, migration, and invasion of tumor cells, and the underlying mechanism could be mainly related to MMP signaling pathway." (PMID 34970146, 2021). "ECM-1 staining was also higher in tumor epithelium than in benign epithelium." (PMID 29858602, 2018). "But the intrinsic mechanism of ECM1 promoting the migration of tumor is very complex, and the induction of EMT may only be one of these links; therefore, other mechanisms of ECM1 by which in the process of HCC cell migration still need to be further discussed." (PMID 27460906, 2016). "ECM1 mRNA in tumor specimen was also dramatically amplified." (PMID 24779890, 2014). "Indeed, ECM1 and perlecan interact during development and in pathological events, including tumor progression." (PMID 25499743, 2014). "Moreover, the same as in the primary tumor, ECM1 was also expressed in metastatic cells of invaded tissues, indicating that the protein was correlated with metastatic potential of tumor cells." (PMID 24779890, 2014).
tumor (continued). "IHC scores were then employed to evaluate the association between ECM1 expression and CRC patient clinicopathological features, revealing the expression of ECM1 to be significantly associated with CRC patient TNM staging (P<0.001), lymph node metastasis (P<0.001), and tumor size (P<0.05)." (PMID 35574325, 2022). "Expression of ECM1 in several types of carcinoma suggests that it may promote tumor development." (PMID 25499743, 2014). "IHC analysis of paired tumour tissue samples from 10 patients confirmed the expression of four markers (BTD, ECM1, MBL2, and RAB5C) in both blood and tissues, as demonstrated in our study." (PMID 40545963, 2025). "The levels of ECM1 and ANXA1 in uEVs were found to be significantly elevated in MMTV-PyMT transgenic mice from week 5 compared to normal mice, with an increase in tumor size." (PMID 39040439, 2024). "Similar results were observed in the 4T1-bearing BALB/c mouse model, where HFD feeding significantly increased ECM1 protein levels in the sEVs, as well as ECM1, MMP3, and S100A/B protein levels in the tumor tissues." (PMID 38402239, 2024). "Prognosis analysis further supported the involvement of ECM1, MMP3, and S100A2 in the development of BC, as indicated by their elevated levels in human tumor biopsies." (PMID 38402239, 2024). "The ECM1 protein is secreted by HER2-overexpressing cancer cells, leading to positive downstream effects on tumor migration and invasion, facilitating tumor progression." (PMID 36936429, 2023). "It is well recognized that ECM1 is closely related to the emergence of BLCA, even as a participant in tumor angiogenesis." (PMID 37124542, 2023). "Recent studies have demonstrated that ECM1, ENPP1, TSPAN12 were involved in tumor invasion and metastasis." (PMID 35645555, 2022). "In vivo analyses confirmed that ECM1 overexpression was able to enhance EMT induction and CRC tumor progression." (PMID 35574325, 2022). "Lastly, to examine the mechanisms whereby ECM1 influences in vivo CRC tumor growth, we generated a xenograft model system using nude mice implanted with HCT116, HCT116-NC, or HCT116-ECM1 cells (n=5 mice/group)." (PMID 35574325, 2022). "And the present study further suggested that ECM1 interacts with α6β4 in AT2 cells and promotes the CSC-like property and tumor initiation of AT2 cells." (PMID 32157214, 2020). "Tumor cells are able to modify ECM by producing EVs that contain extracellular proteins, such as the extracellular matrix protein 1 (ECM-1) and Collagen IV, as well as ECM remodeling enzymes." (PMID 29261132, 2017). "LMVD in the ECM1- and VEGF-C-positive tumor specimens was higher than that in the tissue types with negative staining (P < 0.05)." (PMID 22284579, 2012). "VEGF-C is the most extensively studied molecule for tumor lymphangiogenesis and we found that VEGF-C has potential synergy with ECM1 for facilitating lymphatic metastasis." (PMID 22284579, 2012). "The LMVD in both ECM1- and VEGF-C-positive (E+V+) tumor specimens was higher than that in both the ECM1- and VEGF-C-negative (E-V-) ones (Mann-Whitney test, P = 0.029)." (PMID 22284579, 2012). "The present study highlighted a positive correlation between ECM1 protein expression and LMVD, in both the tumor specimens and the lymph nodes." (PMID 22284579, 2012). "Additionally, in CRC tissues and cell lines, extracellular matrix protein 1 (ECM1) is upregulated and positively related to tumor size and the TNM stage." (PMID 40001878, 2025). "Extracellular matrix protein 1 (ECM-1) is a glycoprotein that usually acts as a functional binding core protein and interacts with a variety of proteins to regulate angiogenesis and tumor growth." (PMID 36411308, 2022). "In summary, we herein found ECM1 to be overexpressed in CRC patient tumors and CRC cell lines, with the expression of this oncogenic factor being related to patient TNM staging, lymph node metastasis, and tumor size." (PMID 35574325, 2022).